ZNF783 (zinc finger protein 783)
Description:
May be involved in transcriptional regulation.
Synonyms: DKFZp667J212
Tractability: Antibody: the Human Protein Atlas places it where antibodies can reach. PROTAC: ubiquitination databases record sites on it.
Gene: Protein-coding gene on chromosome 7 (149,262,171 to 149,297,302, forward strand). Ensembl gene ENSG00000204946.
Subcellular location: Nucleus
Subcellular location (Human Protein Atlas): Cytosol; Plasma membrane
Gene Ontology:
Molecular function: protein binding; DNA-binding transcription factor activity; RNA polymerase II cis-regulatory region sequence-specific DNA binding; identical protein binding
Biological process: regulation of DNA-templated transcription
Cellular component: nucleus
Genetic constraint (gnomAD): Loss-of-function variants: 25 observed, 30.48 expected, observed/expected ratio (o/e) 0.82, 90% interval 0.6 to 1.14. The synonymous counts are far from expectation, so gnomAD's model fits this gene poorly and the ratio says little. Missense variants: 797 observed, 682.84 expected, observed/expected ratio (o/e) 1.17, 90% interval 1.1 to 1.24. Synonymous variants: 369 observed, 287.96 expected, observed/expected ratio (o/e) 1.28, 90% interval 1.18 to 1.4.
Homologues: Orthologues: chimpanzee ZNF783 (98% identical), dog ZNF783 (80% identical), pig ZNF783 (79% identical), Drosophila melanogaster CG10631 (20% identical), zebrafish znf574 (15% identical), Drosophila melanogaster CG11902 (14% identical), Drosophila melanogaster CG11696 (11% identical). Paralogues in human: ZNF212 (39% identical), ZNF865 (15% identical), ZNF366 (14% identical), ZNF710 (14% identical), ZNF667 (13% identical), ZNF671 (13% identical), ZNF662 (11% identical).
Diseases named in the same sentence as ZNF783 in open-access papers:
ZNF783 is named in the same sentence as 1 disease in open-access papers, as found by Europe PMC text mining. Sharing a sentence is not in itself a finding about the gene and the disease.
ZNF783 shares sentences with these, for which no sentence is quoted: tumor (1 paper).